EPS8L1 (EPS8 signaling adaptor L1)
Description:
Stimulates guanine exchange activity of SOS1. May play a role in membrane ruffling and remodeling of the actin cytoskeleton.
Synonyms: DRC3; EPS8R1; PP10566; FLJ20258; MGC23164; MGC4642
Tractability: Antibody: its Gene Ontology location is reachable by antibodies, with medium confidence. PROTAC: ubiquitination databases record sites on it.
Gene: Protein-coding gene on chromosome 19 (55,072,020 to 55,090,124, forward strand). Ensembl gene ENSG00000131037.
Subcellular location: Cytoplasm
Subcellular location (Human Protein Atlas): Cytosol
Gene Ontology:
Molecular function: actin binding; cadherin binding; guanyl-nucleotide exchange factor activity; protein binding; T cell receptor binding
Biological process: positive regulation of ruffle assembly; regulation of Rho protein signal transduction; Rho protein signal transduction
Cellular component: cytosol; extracellular exosome; protein-containing complex; ruffle membrane; plasma membrane; cytoplasm
Genetic constraint (gnomAD): Loss-of-function variants: 106 observed, 91.51 expected, observed/expected ratio (o/e) 1.16, 90% interval 0.99 to 1.36. The synonymous counts are far from expectation, so gnomAD's model fits this gene poorly and the ratio says little. Missense variants: 1,114 observed, 975.93 expected, observed/expected ratio (o/e) 1.14, 90% interval 1.09 to 1.2. Synonymous variants: 506 observed, 427.22 expected, observed/expected ratio (o/e) 1.18, 90% interval 1.1 to 1.27.
Homologues: Orthologues: chimpanzee EPS8L1 (98% identical), macaque EPS8L1 (96% identical), rat Eps8l1 (86% identical), mouse Eps8l1 (86% identical), dog EPS8L1 (82% identical), pig EPS8L1 (77% identical), tropical clawed frog eps8l1 (47% identical), zebrafish eps8l1a (29% identical), Caenorhabditis elegans eps-8 (28% identical), zebrafish eps8l1b (28% identical), Drosophila melanogaster CG8907 (25% identical), Drosophila melanogaster aru (24% identical), and 1 more. Paralogues in human: EPS8 (41% identical), EPS8L2 (40% identical), EPS8L3 (26% identical).
Diseases named in the same sentence as EPS8L1 in open-access papers:
EPS8L1 is named in the same sentence as 15 diseases in open-access papers, as found by Europe PMC text mining. Sharing a sentence is not in itself a finding about the gene and the disease. The quoted sentences say what the papers report.
chronic obstructive pulmonary disease (1 paper, 2024). A chronic and progressive lung disorder characterized by the loss of elasticity of the bronchial tree and the air sacs, destruction of the air sacs wall, thickening of the bronchial wall, and mucous accumulation in the bronchial tree. "The exact function of this protein is unknown, but not so long ago, there appeared data on its high methylation level in smoking patients with chronic obstructive pulmonary disease, as well as on suppression of EPS8L1 in radioresistant clones of pancreatic cancer cell lines." (PMID 38540309, 2024).
depression (1 paper, 2022). "Consequently, further study is needed to understand the underlying mechanism of these DEGs (including Eps8l1, Plcb2, Mpp1, Pidd1) in Asmt-related depression and exercise effects, thus provide new targets for the treatment of exercise for depression." (PMID 35771226, 2022). "In other words, Eps8l1 and Plcb2 may regulate synaptic plasticity by affecting the expression level of Bdnf to participate in the molecular mechanisms of depression." (PMID 35771226, 2022). "Of these, Eps8l1 and Plcb2 were the first time to be proposed as the target genes in depression." (PMID 35771226, 2022). "Overall, Eps8l1 may take part in molecular mechanism of depression pathology and exercise effects via regulating synaptic plasticity and actin structures." (PMID 35771226, 2022).
growth retardation (1 paper, 2025). "To determine how specific the upregulation of EPS8L1 is to PE patients, we analyzed placental EPS8L1 levels in merged pool of additional cohorts (Aachen) that includes samples taken from patients with IUGR (intrauterine growth retardation)." (PMID 41188995, 2025).
lung carcinoma (1 paper, 2018). "Therefore, if the M.tuberculosis sRNA_1414 is transferred to the host during theinfection, it may lead to lung cancer metastasis in later stagefunctioning similar to EPS8L1 and SORBS1." (PMID 30237679, 2018).
meningioma (1 paper, 2017). A generally slow growing tumor attached to the dura mater. "The trends of gene expression profiles of candidates such as EFCAB2, EPS8L1, NOL3, PAIP1 and SNX1 showed elevated expression in meningiomas compared to controls, while CAMK2N1, CRYM and PRPSAP2 showed decreased expression levels in meningiomas compared to the controls." (PMID 28938569, 2017).
neuroblastoma (1 paper, 2022). Neuroblastoma (NB) is the most common solid, extracranial childhood tumor. "The screening results of the RF classifier showed that EPS8L1, PLCD4, CHD5, NTRK1, and SLC22A4 were the most characteristic DEG genes among high-risk neuroblastoma-related genes." (PMID 35911385, 2022). "The screening results of RF showed that EPS8L1, PLCD4, CHD5, NTRK1, and SLC22A4 were the feature differentially expressed genes (DEGs) of high-risk neuroblastoma." (PMID 35911385, 2022).
preeclampsia (1 paper, 2025). Preeclampsia is a hypertensive disorder of pregnancy that is characterized by new-onset hypertension with proteinuria presenting after 20 weeks of gestation, and depending on mild or severe forms may initially present with severe headache, visual disturbances, and hyperreflexia. "EPS8L1 knockout in trophoblast in vitro is lethal, and its overexpression alters trophoblast behaviors characteristic of preeclampsia." (PMID 41188995, 2025).
tauopathy (1 paper, 2023). Neurodegenerative disorders involving deposition of abnormal tau protein isoforms (tau proteins) in neurons and glial cells in the brain. "Erdr1, a stress-induced cell survival factor, was downregulated in APOE4 mice relative to APOE3 and APOE2 mice while Eps8l1, a tauopathy-related Bin1-responsive gene, was downregulated in APOE3 mice relative to APOE4 and APOE2 mice." (PMID 37337279, 2023).
cancer (4 papers, 2014 to 2025). A tumor composed of atypical neoplastic, often pleomorphic cells that invade other tissues. "Consistently, Eps8l1 is also a key molecule in cancer research." (PMID 35771226, 2022). "Its precise role in cancer initiation or progression in mice has not been elucidated, largely because it shares redundant biological functions with other family members, namely Eps8L1, Eps8L2 and Eps8L3." (PMID 25359883, 2014).
tumor (2 papers, 2025). "Among them, the epithelial cell differentiation-related KRT gene family, the cell cycle regulation gene FAM83H, and the tumor metastasis-related genes EPS8L1 and TNS4 were upregulated in metastatic TDLNs." (PMID 39753715, 2025). "In contrast, Tum_3 tumor cells primarily expressed genes linked to epithelial differentiation and keratinization, such as CNFN, EPS8L1, and HEPHL1." (PMID 40470730, 2025).
brain diseases (1 paper, 2022). "Furthermore, GO terms analysis showed that Eps8l1 was involved in Rac guanyl-nucleotide exchange factor activity, which has been found to regulate glucose metabolism in brain and then relate to brain diseases." (PMID 35771226, 2022).
neurodevelopmental disorder (1 paper, 2022). A behavioral and cognitive disorder with onset during the developmental period that involves impaired or aberrant development of intellectual, motor, or social functions. "Cask, another first-order neighbor of Eps8l1, belongs to the membrane-associated guanylate kinase (MAGUK) family, and improve neurodevelopmental disorders by regulating synaptic plasticity." (PMID 35771226, 2022).
EPS8L1 also shares sentences with these, for which no sentence is quoted: asthma (1 paper); bladder cancer (1); pancreatic cancer (1).